RORA (RAR related orphan receptor A)
Diseases named in the same sentence as RORA in open-access papers (continued):
Sharing a sentence is not in itself a finding about the gene and the disease.
tumor (continued). "Another study found that ILC2s were markedly absent in RORα-deficient mice, and this loss was accompanied by an increase in tumor burden; in human, the high ILC2 gene signature in tumor was an independent predictor of better outcome in CRC patients." (PMID 35720302, 2022). "However, depletion of BMAL1 promotes cell growth and almost completely rescues the block in cell viability and the apoptosis induced both by SR1078 and RORα overexpression, suggesting that the anti-tumor activity of RORα is dependent on BMAL1." (PMID 34183658, 2021). "The extensively low expression of Rorα indicates an essential role in tumor progression." (PMID 33664254, 2021). "In order to confirm that RORα deletion results in ablation of ILC2s, we analysed the number and function of T cells and ILCs within the colons of untreated Rorαfl/flIl7rCreT/+ and Rorα+/+Il7rCreT/+ mice, compared to tumour-bearing mice." (PMID 33535624, 2021). "Further anti-tumor effect of Rorα activation was confirmed in a cSCC mouse model in vivo." (PMID 33664254, 2021). "Furthermore, we calculated the percentage of cells with Rorα > 1 count, that more Rorα positive cells were exhibited in normal (72.49%) keratinocytes than that in the tumor (33.15%) cells." (PMID 33664254, 2021). "In addition, RORα contributes to the intracellular DNA damage response, which is a checkpoint that determines cell fate, progression to a tumor or cell cycle blockade, and apoptosis during the early stage of tumorigenesis." (PMID 34588606, 2021). "RORA can then suppress tumor progression through regulation of the Wnt signaling pathway." (PMID 34666800, 2021). "Furthermore, RORα is involved in various physiological processes, such as the circadian clock, inflammation, tumorigenesis, and metabolic diseases, and it is a tumor suppressor in many types of cancer." (PMID 34588606, 2021). "Various studies have indicated that RORA functions as a tumor suppressor." (PMID 34666800, 2021). "Notably, the expression of RORα in 4T1 cells significantly inhibited cancer metastasis, reduced macrophage accumulation, and enhanced M1-like macrophage differentiation in tumor tissue." (PMID 34639006, 2021). "However, SR1078 was not able to block tumor growth in a non-MNA xenograft model of SK-N-AS cells (p = 0.5116), suggesting that the tumor-suppressive function of RORα activation is MYCN-dependent." (PMID 34183658, 2021). "Qualitative analysis could only be performed for RORα because of a limited availability of tumor tissue in paraffin blocks from many patients." (PMID 33227893, 2020). "RORα may be involved in the development of GC by affecting different tumor molecules or signaling pathways." (PMID 33336001, 2020). "Retinoid Acid Receptor-Related Orphan Receptor Alpha (RORA) is a suppressor for tumor and could be involved in immunity, inflammation metabolism, and tumor initiation." (PMID 32806547, 2020). "Furthermore, the spread of metastatic A9 tumour cells was higher when compared to metastatic A9+IL-33, in both WT and RORα−/− bone marrow chimeric mouse models." (PMID 29440650, 2018). "RORα is also involved in inhibiting cell proliferation as a tumor suppressor." (PMID 29904382, 2018). "Agonists or inverse agonists for RORα and RORγ might be efficiently inhibiting tumor growth and progression through activation or inactivation so that their ligands or targets, such as vitamin D3 derivatives and AR, become valid or invalid." (PMID 29904382, 2018). "Another promising new strategy for anticancer therapy might involve directly targeting tumor cells with RORα- and RORγ-specific modulators due to the correlations between high or low expression of RORα and RORγ and tumor progression." (PMID 29904382, 2018).
tumor (continued). "In contrast, the suppression of ILC2 number and function in mice transplanted with RORα−/− BM allowed the metastases to increase, suggesting the importance of the RORα transcription factor and the presence of functional ILC2s for the proper development of anti-tumour immune responses." (PMID 29440650, 2018). "In order to assess this hypothesis, the mRNA levels of RORA in the tumor and normal epithelial tissues from 44 OSCC patients were studied using the quantitative real-time PCR." (PMID 30293994, 2018). "Some studies suggest that RORα is a tumor suppressor and a potential therapeutic target for BC; and based on the limited researches on RORβ in cancer, RORβ might be a tumor suppressor as well." (PMID 29904382, 2018). "We have experimentally validated a group of oncomiRs (miR-503-5p, miR-450b-5p, miR-27a-3p, miR-181a-5p and miR-183-5p) in repressing the expression of RORA, which is proven to be a major tumor suppressor by clinic sample analysis, as well as by cell proliferation and nude mice assays." (PMID 30293994, 2018). "Accumulative evidence has shown that Bmal1 and RORα are tumor suppressors." (PMID 27602774, 2016). "Recent studies indicate that RORα functions as a tumor suppressive molecule." (PMID 27602774, 2016). "Together, these results indicate that RORα is a potent tumor suppressor." (PMID 23443091, 2012). "The orphan nuclear receptor RORα has recently been identified as a potent tumor suppressor." (PMID 23443091, 2012). "Furthermore, reduced expression and hypoactivation of RORα in several human tumors, combined with their functional role as tumor suppressors, make RORα an attractive target for cancer therapy." (PMID 23443091, 2012). "Moreover, PLG, another RORα target gene displayed by the present study, is involved in fibrinolysis, wound healing, tumor growth and metastasis." (PMID 21818335, 2011). "In recent years, the study of RORα as a tumor therapeutic target has become a hot spot, especially the search for agonists or drugs from natural chemicals to promote the expression and activation of RORα, which has broad application prospects in the field of cancer therapy." (PMID 41425709, 2025). "However, few studies between RORα and aerobic glycolysis in tumor." (PMID 38184549, 2024). "Moreover, SR1078 as a RORα activator was identified to the function of tumor suppression." (PMID 38184549, 2024). "In addition, we confirmed the anti-tumor effect of Rorα activation in a cSCC mouse model in vivo." (PMID 33664254, 2021). "The oncogenic function of EZH2 may be augmented by the methylation-dependent degradation of tumour suppressive proteins such as RORα in cancer, thus providing an attractive prototype, suggesting the cross-regulation of oncogenes and tumour suppressor genes for efficient tumour progression." (PMID 26757928, 2016). "Among the predicted activated CP, in CIMP vs. LOW PM cell lines, were those related to RORA, RAS processing and PPAR signaling, primarily involved in tumor cell proliferation and invasion." (PMID 39966970, 2025). "In summary, RORA and SPARC are crucial downstream targets of TET2 that connect TET2 and its tumour suppression effects." (PMID 37620362, 2023). "To further investigate the influence of RORα/γ on CRC patient survival, we collected tumour tissues from CRC patients and performed immunohistochemical (IHC) analysis of the RORα/γ proteins." (PMID 36316442, 2022).
tumor (continued). "The expression of CRY2, PER2, PER3 and RORA was correlated with TNM stage, T stage, and tumor differentiation in KIRC patients (p < 0.05)." (PMID 34977153, 2021). "Meanwhile, tumor suppressors, including KLF12, PRKG1, TRPS1, NOTCH1, RORA, were downregulated in the HSPA8high group." (PMID 33926391, 2021). "Using cartilage samples collected from amputation or tumor resection surgery as normal control and TKA surgery as OA cartilage, we performed immunohistochemistry (IHC) staining to detect RORα expression level." (PMID 34584074, 2021). "Age- and gender-matched Rorαfl/flIl7rCreT/+ and littermate control Rorα+/+Il7rCreT/+ mice underwent the CAC protocol, and tumour development was monitored by endoscopy." (PMID 33535624, 2021). "We also observed that tumor suppressors, including KLF12, PRKG1, TRPS1, NOTCH1, and RORA, were downregulated in the HSPA8high group." (PMID 33926391, 2021). "We then established TC1 tumours in the four groups of mice: RAG−/− alone; WT alone; WT → RAG−/−; and RORα−/− → RAG−/−." (PMID 29440650, 2018). "For the first time, we discovered a miRNAs-mediated TFs network, which led to a discovery of a master tumor suppressor of OSCC progression, RORA, whose expression was cooperatively controlled by a group of regulated miRNAs." (PMID 30293994, 2018). "Among these TFs, RORA is further demonstrated to be widely suppressed in OSCC samples, and represses cell proliferation in vitro and tumor growth in nude mice." (PMID 30293994, 2018). "We found the similar level of tumour growth reduction in the WT, WT → RAG−/− and RORα−/− → RAG−/− animals, as compared to the tumour growth level in the RAG−/− only mice." (PMID 29440650, 2018). "To determine whether decreased RORA expression in OSCC was caused by the onco-related miRNAs, we selected five miRNAs (miR-503-5p, miR-450b-5p, miR-27a-3p, miR-181a-5p, and miR-183-5p) which linked to tumor proliferation in a variety of cancers, to evaluate their regulation effects on RORA." (PMID 30293994, 2018). "The vitamin D signaling pathway plays a critical role in tumor suppression through interactions with its active metabolites, such as 1,25-dihydroxyvitamin D3, which bind to the vitamin D receptor (VDR) and other nuclear receptors like RORα and RORγ." (PMID 40331942, 2025). "Moreover, the subcutaneous tumor group of RORα-KO plus 3PO or RORα-KO plus DHEA revealed a reduction of Ki-67 and PCNA expression levels compared with RORα-KO plus Vehicle group." (PMID 38184549, 2024). "Nuclear receptors RORa, NR2F6 and HNF4G are uncovered as candidate transcriptional drivers of these cells whilst closure of binding sites for E2F2 and E2F4 indicate post-treated tumour having low proliferative capacity." (PMID 39341888, 2024). "As an independent predictor of the status of sentinel lymph node, tumor infiltrating lymphocytes have been gathering more and more attention; therefore, the probable correlation between TIMELESS and RORA expression and immune infiltration levels in NSCLC was assessed." (PMID 35078435, 2022). "Besides, the overlapping genes that exhibited similar expression levels in tumor samples from both the TCGA and ICGC databases were shown in a Venn diagram, including DBP, NPAS2, PER1, RORA, and TIMELESS." (PMID 34745328, 2021). "In addition, compared to control tumors, tumor cell proliferation was significantly lower in tumors that were both treated with SR1078 and overexpressing RORα (p < 0.0001 and p = 0.0012, respectively)." (PMID 34183658, 2021). "Importantly, the anti-tumor activity of SR1078 and RORα is abolished following depletion of BMAL1, further supporting that the core clock component BMAL1 functions as a tumor suppressor in NB." (PMID 34183658, 2021). "By comparing gene expression profiles between polarized and non-polarized mammary epithelial organoids, we identified RORα as a major regulator of mammary tissue polarity with inhibitory activity on tumor invasion." (PMID 34639006, 2021).
tumor (continued). "Currently, there are no clinical trials related to RORα for cancer treatment, even though it has been shown to be a tumor suppressor in many preclinical studies." (PMID 32610705, 2020). "To do so, we analyzed the growth of TC1 tumours in RAG−/− mice (lacking T and B cells) that had been supplemented with splenocytes obtained from either WT or RORα−/− animals (WT → RAG−/− and RORα−/− → RAG−/−) and compared them to the growth of TC1 tumours in WT or RAG−/− control animals." (PMID 29440650, 2018). "While survival was independent of RORα expression in the current study, RORα-related anti-tumor mechanisms could potentially be amplified via melatonin at therapeutic doses." (PMID 39201396, 2024). "Since the protein levels in tumor tissues could be regulated by transcription, mRNA translation, protein stability, or proteasome-mediated degradation, we speculated that CASC2 might upregulate RORA protein expression by maintaining the protein stability." (PMID 34408982, 2021). "The classical ability of RORα to regulate target gene expression is key for activation of tumor-suppressive target genes 36, although a transcription-independent function of RORα via a noncanonical pathway can potentiate tumor-suppressive roles." (PMID 34588606, 2021). "Indeed, CRY2, PER1, and RORA were downregulated, and TIMELESS was upregulated in tumor tissues, suggesting that TIMELESS may play a different role in HCC." (PMID 34745328, 2021). "We addressed whether the effects on tumour growth within the RORα−/− mice were due to the lack of ILC2s and not due to the lack of functional T or B cells." (PMID 29440650, 2018). "The crucial role of RORs as anti-tumor factors is further supported by studies showing a negative correlation of RORα and RORγ expression with pathological grade, increased incidence of tumor recurrence, vascular invasion, clinical outcome, including distance metastasis free survival and OST." (PMID 27542227, 2016). "RORα was shown to inhibit pyruvate dehydrogenase kinase 2 (PDK2) expression and phosphorylation, thereby promoting aerobic glycolysis rather than oxidative phosphorylation, whereas reduced RORα expression in tumor cells promotes oxidative phosphorylation and tumor cell growth." (PMID 26878025, 2015). "Both SR1078 and genetic overexpression of RORα effectively restore BMAL1 expression and oscillation, and block tumor growth in MNA, but not in non-MNA orthotopic xenografts, suggesting that the anti-tumor effect of SR1078 is MYCN-dependent." (PMID 34183658, 2021).
cancer (90 papers, 2009 to 2025). A tumor composed of atypical neoplastic, often pleomorphic cells that invade other tissues. "Target genes associated with several diseases, including cancer, are transcriptionally regulated by RORα." (PMID 34588606, 2021). "Our data suggest that ROS is the major mediator of RORα function in regulating cytokine expression and cancer-associated macrophage infiltration." (PMID 34639006, 2021). "Restoring RORα expression suppresses cancer metastasis and ROS-associated inflammation; therefore, enhancing RORα expression or inducing RORα activation with agonists is a potential strategy to suppress ROS-associated cancer progression." (PMID 34639006, 2021). "Among these targets, we found that RORA was widely investigated in previous studies and associated with cancer progression." (PMID 34479497, 2021). "Further cancer hallmark analysis reveals that several core clock genes highly correlate with apoptosis and cell cycle such as RORA and PER2." (PMID 31881010, 2019). "Recent studies have shown that RORα is associated with cancer prognosis through the modulation of cell proliferation." (PMID 28052040, 2017). "The data indicated that there was a positive correlation between RORα and ILC2s-associated receptors or signature cytokines in cancer patients, respectively." (PMID 24741632, 2014). "Furthermore, RORα has been implicated in many pathophysiological processes including circadian rhythm, immunity, metabolic pathways and cancer." (PMID 30987323, 2019). "In fact, RORα is also known to play a role in the circadian cycle, and a cross-talk between this and cell cycle control is currently emerging as an important element of cancer susceptibility." (PMID 23922987, 2013). "The protein known as retinoic acid receptor-related orphan receptor α (RORα) activates specific genes in response to the daily cellular changes associated with circadian rhythms, and disruption of its activity is associated with cancer, inflammation and metabolic diseases." (PMID 34588606, 2021). "RORA inhibits cancer cell proliferation and migration by suppressing the Wnt/β-catenin signaling pathway." (PMID 40638694, 2025). "Currently, research on Rorα has predominantly centered on its roles in cancer and the nervous system." (PMID 40563503, 2025). "In recent years, the role of RORA in multiple diseases, particularly in inflammatory diseases, metabolic disorders, neurological conditions, and cancers, has garnered considerable attention." (PMID 40638694, 2025). "Reportedly, RORα is one of circadian rhythm genes and is involved in multiple metabolic cycles in mammals, and its dysregulation results in disease and even cancer." (PMID 38184549, 2024). "Activation of RORα mitigates cancer progression by decreasing invasiveness and proliferation in both human and mouse cSCC cell lines." (PMID 39518891, 2024). "In recent years, many independent studies on RORα have discovered its potential role in human cancers." (PMID 38725854, 2024). "Our findings identify RORα as a direct target of PS VII for the first time, clarifying the key role of RORα in glycolysis-induced cancer drug resistance and metastasis." (PMID 38725854, 2024). "Treatment with the AMPK activator AICAR results in a substantial elevation of RORα levels in cancer cells." (PMID 39518891, 2024). "One of the pathways that contribute to the reduction of RORα in cancer cells is reduced activation of AMP-activated protein kinase (AMPK)." (PMID 39518891, 2024). "Concurrently, activation of AMPK increases translocation of RORα to the promoters of tumor suppressor genes, increasing induction of apoptosis in cancer cells." (PMID 39518891, 2024). "In patients suffering from cancer, nobiletin-mediated activation of RORα suppresses cancer cell viability and proliferation." (PMID 39518891, 2024). "The results revealed significant downregulation of CLOCK, PER1, PER2, PER3, CRY1, CRY2, REV-ERBα, and RORα in cancer tissues compared with matched normal tissues." (PMID 37240325, 2023).